FCER1A (Fc epsilon receptor Ia)
Diseases named in the same sentence as FCER1A in open-access papers (continued):
Sharing a sentence is not in itself a finding about the gene and the disease.
tumor (25 papers, 2010 to 2025). "The significant upregulation of MX2 in high-risk patients, along with the reduced expression of FAM50B, FUCA1, AKAP6, and FCER1A in this group, further supports their potential roles in tumour progression and immune regulation." (PMID 40329678, 2025). "Among these genes, FCER1A and CH25H have previously been reported to be overexpressed in anti-inflammatory M2 macrophages, and FCER1A+ TAMs have been reported to promote tumor progression by engaging in a positive feedback loop with tumor-initiating cells." (PMID 38722600, 2024). "Nevertheless, the composition of the immune infiltrate in both the perilesional skin and the tumour tissue was overall similar in Fcer1a–/– and WT mice, apart from a minor reduction in neutrophils in the tumours from Fcer1a–/– mice." (PMID 31931959, 2020). "Bulk RNA-seq analysis of CD1c+CD14+ cells sorted from tumor-invaded lymph nodes indicated that they displayed a similar expression profile as blood DC3s (high expression of cDC2 markers such as CLEC10A and FCER1A combined with low expression of monocyte-associated markers such as C5AR1 and SOD2)." (PMID 32610077, 2020). "Using the two-stage inflammation-driven model of epithelial carcinogenesis, we found that mice lacking FcεRI (Fcer1a–/–) were significantly less susceptible to tumour development." (PMID 31931959, 2020). "Next, we selected myeloid cell clusters on the basis of the expression of myeloid cell markers (“CD14+”, “FCER1A-”) by the scGate R package from GSE207422 (LUAD samples) and GSE205506 (CRC tumour samples)." (PMID 38773508, 2024). "In the mDCs group, CD1C+ mDC (CD1C, FCER1A, and CLEC10A) were reduced in the tumor compartment compared to the adjacent kidney." (PMID 36180422, 2022). "In the HPA database, protein expressions of the seven genes (ADAMTS8, CCR2, CYSLTR2, FAM129C, FCER1A, GAPT, PKHD1L1, and ZNF831) were markedly low in tumor tissues with less intense antibody staining and fewer stained cells in LUAD." (PMID 36033829, 2022). "We were able to rule out that FCER1A or SVEP1 is involved in the observed tumor dormancy-inducing activity of PEAR1." (PMID 41185039, 2025). "We observed that FceR1a was present at higher levels on SSMs, as compared to MSMs, in both non-draining and tumor-draining lymph nodes." (PMID 34168645, 2021).
cancer (11 papers, 2007 to 2025). A tumor composed of atypical neoplastic, often pleomorphic cells that invade other tissues. "We identified cDC2s (CD1C+FCER1A+) as the predominant cDC subset, paralleling with previous pan-cancer single-cell data." (PMID 36198671, 2022). "The central gene is PIK3R1 in Module 0, which module contains eight DEGs related to classical cancer pathways (FCER1A, GNG11, IGF1, LIFR, PDK4, PIK3R1, RCAN2, and UGCG)." (PMID 31119098, 2019). "Microarray analysis of cancer tissues from AOM/DSS and AOM/DSS/Ab mice revealed profound differences in the expression of genes associated with mast cells, namely Mctp1, Mctp2, Mctp4, Cma1, Fcer1a, Pla2g2e, and Cpa3." (PMID 37185713, 2023). "Compared to S100A10, presently much fewer studies explore the relations between FCER1A, FNTA, and cancer." (PMID 36430822, 2022). "Those 6 genes in the model (PDK4, MPP1, ASGR1, MS4A14, FCER1A and MX2), rarely reported in cancers, were found to be significantly related to the prognostic survival of KIRC patients." (PMID 34606472, 2021). "Furthermore, three DEGs (FCER1A, EDNRB, and TGFBI) in the model of relapse showed prognostic significance for predicting the survival of patients with cancer through Cox proportional hazards regression model-based survival analysis." (PMID 33138797, 2020). "On the opposite side, the roles of FCER1A and FNTA in cancer and therapeutic resistance have not been well studied and thus could be novel markers of therapeutic resistance in CML." (PMID 36430822, 2022).
infection (6 papers, 2016 to 2024). The state of being infected such as from the introduction of a foreign agent such as serum, vaccine, antigenic substance or organism. "The effect of Fcer1a polymorphism on inflammatory responses may also, in turn, affect individual susceptibility to infection." (PMID 36645701, 2023). "The Fc epsilon receptor expressed in dendritic cells, FCER1A, was upregulated in the lymph nodes at 1 dpi, implying that pathogen sensing, phagocytosis, and antigen presentation occurred in the lymph nodes in the early phase of infection." (PMID 38847223, 2024). "Notably, FCER1A, the Fc fragment of IgE receptor Ia that binds to the Fc region of IgE and is responsible for initiating the allergic response, was upregulated by HP-PRRSV-JXA1 infection." (PMID 33726857, 2021).
bacterial infection (3 papers, 2022 to 2025). "Based on their average logistic regression coefficients, the five most important genes for bacterial classification were CEPT (+), RPGRIP1 (-), FCER1A (-), IFI27 (-), and PDE9A (-), where plus indicates upregulation and minus indicates downregulation for bacterial infection." (PMID 35184750, 2022).
FCER1A also shares sentences with these, for which no sentence is quoted: atopic dermatitis (5 papers); chronic spontaneous urticaria (5); basophilic leukaemia (4); allergic asthma (3); Autoimmunity (3); systemic lupus erythematosus (3); endometriosis (2); helminth infection (2); nasal polyps (2); airway allergies (1); allergic conjunctivitis (1); autoimmune urticaria (1); bacterial meningitis (1); bronchiectasis (1); bronchiolitis (1); Burkitt lymphoma (1); celiac disease (1); chronic kidney disease (1); colitis (1); colon cancer (1); conjunctivitis (1); eosinophilic leukemia (1); esophagitis (1); food allergy (1); gastritis (1); Gastrointestinal inflammation (1); Graves disease (1); hay fever (1); immune system disease (1); infectious disease (1).
A further 14 diseases each share a sentence with FCER1A in 1 paper.